ZDHHC18 (zDHHC palmitoyltransferase 18)
Description:
Palmitoyltransferase that catalyzes the addition of palmitate onto various protein substrates, such as CGAS, HRAS and LCK. Acts as a negative regulator of the cGAS-STING pathway be mediating palmitoylation and inactivation of CGAS. May also have a palmitoyltransferase activity toward the beta-2 adrenergic receptor/ADRB2 and therefore regulate G protein-coupled receptor signaling.
Synonyms: DHHC-18; DKFZp667O2416; DHHC18
Tractability: Antibody: UniProt predicts a signal peptide or a membrane-spanning region. PROTAC: ubiquitination databases record sites on it; its protein half-life has been measured.
Gene: Protein-coding gene on chromosome 1 (26,826,688 to 26,857,604, forward strand). Ensembl gene ENSG00000204160.
Subcellular location: Golgi apparatus membrane
Subcellular location (Human Protein Atlas): Cytosol; Golgi apparatus
Gene Ontology:
Molecular function: palmitoyltransferase activity; protein-cysteine S-palmitoyltransferase activity
Biological process: negative regulation of cGAS/STING signaling pathway; negative regulation of innate immune response; peptidyl-L-cysteine S-palmitoylation; protein targeting to membrane
Cellular component: Golgi apparatus; Golgi membrane; endoplasmic reticulum
Genetic constraint (gnomAD): Loss-of-function variants: 23 observed, 35.8 expected, observed/expected ratio (o/e) 0.64, 90% interval 0.46 to 0.91. The upper end of that interval is the gene's LOEUF score, 0.91, which puts it in group 3 of 6, group 1 being the genes least tolerant of losing a copy. Missense variants: 406 observed, 487.43 expected, observed/expected ratio (o/e) 0.83, 90% interval 0.77 to 0.9. Synonymous variants: 185 observed, 196.63 expected, observed/expected ratio (o/e) 0.94, 90% interval 0.83 to 1.06.
Homologues: Orthologues: chimpanzee ZDHHC18 (99% identical), macaque ZDHHC18 (99% identical), pig ZDHHC18 (95% identical), dog ZDHHC18 (94% identical), rat Zdhhc18 (94% identical), mouse Zdhhc18 (93% identical), guinea pig ZDHHC18 (76% identical), zebrafish zdhhc18a (64% identical), zebrafish zdhhc18b (63% identical), rabbit ZDHHC18 (63% identical), Caenorhabditis elegans dhhc-2 (39% identical), Drosophila melanogaster CG1407 (17% identical), and 8 more. Paralogues in human: ZDHHC14 (61% identical), ZDHHC9 (48% identical), ZDHHC20 (19% identical), ZDHHC1 (18% identical), ZDHHC2 (18% identical), ZDHHC15 (18% identical), ZDHHC3 (16% identical), ZDHHC19 (16% identical), ZDHHC7 (16% identical), ZDHHC12 (15% identical), ZDHHC4 (15% identical), ZDHHC11 (14% identical), and 5 more.
Diseases named in the same sentence as ZDHHC18 in open-access papers:
ZDHHC18 is named in the same sentence as 22 diseases in open-access papers, as found by Europe PMC text mining. Sharing a sentence is not in itself a finding about the gene and the disease. The quoted sentences say what the papers report.
glioma (7 papers, 2019 to 2026). A benign or malignant brain and spinal cord tumor that arises from glial cells (astrocytes, oligodendrocytes, ependymal cells). "In addition, poor prognosis in patients with glioma associates with high co-expression levels of ZDHHC18 and ZDHHC23." (PMID 30658672, 2019). "Among these studies, high expression of ZDHHC18 was found to be an unfavorable prognostic factor for liver cancer and glioma." (PMID 37434393, 2023). "Patients with high ZDHHC18 expression had poor overall survival rate compared with those with low ZDHHC18 expression in renal cancer, liver cancer and glioma." (PMID 35297315, 2022). "Herein, we studied the function of DHHC family proteins in gliomas and found that ZDHHC18 and ZDHHC23 are preferentially expressed in GBMs in comparison to LGGs." (PMID 30658672, 2019). "In these datasets, ZDHHC18 or ZDHHC23 was also found to be highly expressed in the GBM samples compared to that in the low-grade gliomas (LGGs) and normal brain tissues." (PMID 30658672, 2019). "zDHHC18 is a mesenchymal glioma stem cell marker, whereas zDHHC23 is a glioma stem cell marker." (PMID 38293675, 2023). "zDHHC18 and zDHHC23 can target different subpopulations of glioma stem cells in specific settings." (PMID 38293675, 2023). "Thus, stress conditions similar to those found in the pseudopallisading necrotic regions may select for mesenchymal glioma cells with high expression of ZDHHC18." (PMID 30658672, 2019). "It was found that ZDHHC5, ZDHHC17, ZDHHC18, and ZDHHC23 promote cellular self‐renewal by targeting glioma stem cells, which in turn induces malignant progression of tumor cells." (PMID 37434393, 2023). "We then investigated the relationship between clinicopathological characteristics of patients and ZDHHC18 and ZDHHC23 expression levels in 90 glioma tissues." (PMID 30658672, 2019). "The prognostic value of ZDHHC18 and ZDHHC23 co-expression in the overall survival (OS) and disease free survival (DFS) of patients with glioma was examined using Kaplan–Meier survival curves." (PMID 30658672, 2019). "Significant up-regulation of ZDHHC18 and ZDHHC23, especially the latter, was observed in a comparative analysis of 176 normal brain tissues and 2357 glioma tissues." (PMID 30658672, 2019). "ZDHHC18 and ZDHHC23 could target the glioma stem cells of different GBM subsets in the context of their specific niches and regulate the cellular plasticity of these subtypes." (PMID 30658672, 2019). "Thus, expression levels of ZDHHC18 and ZDHHC23 were positively correlated with the increasing tumor grade, both in the publicly available databases and in our cohort of primary tumor specimens, and might, therefore, constitute novel prognostic biomarkers for gliomas." (PMID 30658672, 2019).
glioblastoma (5 papers, 2019 to 2026). The most malignant astrocytic tumor (WHO grade IV). "Furthermore, in mesenchymal glioblastoma, ZDHHC18 enhances the stability of BMI1 to promote the survival of glioblastoma stem cells (GSCs) in stressful microenvironments." (PMID 37161425, 2023). "The different anatomical regions of glioblastoma were analyzed by immunofluorescence using antibodies against ZDHHC18 and ZDHHC23, which demonstrated that both ZDHHC18 and ZDHHC23 were mostly localized in the nucleus and cytoplasmic vesicles around the nucleus." (PMID 30658672, 2019). "In addition, higher expression levels of MMP9, TERT, VEGFA, ZDHHC18, CHEK2, and ADM elevate the probability of predicting glioblastoma." (PMID 40867242, 2025). "Additionally, high expression of ZDHHC18 relates to the mesenchymal molecular phenotype and that of ZDHHC23 is related to the proneural phenotype in glioblastomas, respectively." (PMID 40814339, 2025).
ovarian carcinoma (5 papers, 2022 to 2025). A malignant neoplasm originating from the surface ovarian epithelium. "ZDHHC18 has been reported to catalyze the palmitoylation of MDH2 and promote the development of ovarian cancer." (PMID 39913299, 2025). "ZDHHC18 functions as a palmitoyltransferase for MDH2, promoting the formation of ovarian cancer by maintaining mitochondrial respiration and reinstating the growth and clonogenic potential of ovarian cancer cells." (PMID 39148124, 2024).
astrocytoma (2 papers, 2025 to 2026). "Analysis of the SHAP values for the remaining genes revealed that increased expression of ZDHHC18, HDAC1, and TUBB6 enhances the probability of predicting astrocytoma, while elevated expression of TERT, TRIM67, NOG, KCNIP2, and KCNJ11 increases the probability of predicting oligodendroglioma." (PMID 40867242, 2025).
acute renal failure (1 paper, 2025). "The results of sCr and BUN measurements indicated that the severity of acute renal failure was not different between WT and Zdhhc18-KO mice on day 2 following FA administration." (PMID 39913299, 2025).
chronic kidney disease (1 paper, 2025). Impairment of the renal function secondary to chronic kidney damage persisting for three or more months. "ZDHHC18 is upregulated in fibrotic kidneys of patients with chronic kidney disease." (PMID 39913299, 2025). "We detected ZDHHC18 expression in microdissected kidney samples from patients with chronic kidney disease (CKD)." (PMID 39913299, 2025).
renal fibrosis (1 paper, 2025). A final common manifestation of a wide variety of chronic kidney diseases characterized by glomerulosclerosis and tubulointerstitial fibrosis. "RNA-Seq data showed Zdhhc18 upregulation in fibrotic kidneys of UUO mice or mice with folic acid–induced (FA-induced) renal fibrosis." (PMID 39913299, 2025). "Collectively, these data demonstrate that Zdhhc18 overexpression in renal TECs promotes renal fibrosis and inflammation in mouse CKD." (PMID 39913299, 2025). "In sum, data from the UUO and FA models demonstrate that TEC-specific KO Zdhhc18 reduced renal fibrosis and inflammation in mouse CKD." (PMID 39913299, 2025). "Quantitative real-time PCR (qRT-PCR) and Western blot (WB) analysis confirmed that the expression of ZDHHC18 was upregulated during renal fibrosis." (PMID 39913299, 2025). "Further investigation of the specific contribution of endothelial ZDHHC18 to renal fibrosis progression would provide valuable insights into its cell-type–specific functions and therapeutic potential." (PMID 39913299, 2025). "We also used the FA model to detect the function of Zdhhc18 overexpression in renal fibrosis." (PMID 39913299, 2025). "Ultimately, the expression of renal fibrosis markers in FA-induced Zdhhc18-KO mice was reduced." (PMID 39913299, 2025). "Consequently, we propose that ZDHHC18 plays a critical role in HRAS palmitoylation during renal fibrosis." (PMID 39913299, 2025). "We also showed that ZDHHC18 is a key molecule involved in the communication between the 2 signaling pathways, suggesting that ZDHHC18 is a therapeutic target for the treatment of renal fibrosis." (PMID 39913299, 2025). "In contrast, ZDHHC18 overexpression exacerbated progressive renal fibrosis." (PMID 39913299, 2025). "We identified ZDHHC18 as a promoter of renal fibrosis by using CKO mice." (PMID 39913299, 2025). "Here, we found that the expression of ZDHHC18 was markedly upregulated during renal fibrosis." (PMID 39913299, 2025). "We hypothesize that ZDHHC18 affects renal fibrosis through the palmitoylation of HRAS." (PMID 39913299, 2025). "Knocking out ZDHHC18 in renal TECs inhibited the expression of partial EMT–related genes and alleviates renal fibrosis phenotypes in vivo." (PMID 39913299, 2025). "Subsequently, we found that knocking out Zdhhc18 in renal TECs markedly inhibited UUO- and FA-induced renal fibrosis." (PMID 39913299, 2025). "We found that ZDHHC6, ZDHHC9, and ZDHHC18 could catalyze HRAS palmitoylation but that the expression of ZDHHC6 and ZDHHC9 was downregulated during renal fibrosis." (PMID 39913299, 2025). "In this study, we observed that expression of the palmitoyltransferase ZDHHC18 was significantly elevated in unilateral ureteral obstruction (UUO) and folic acid–induced (FA-induced) renal fibrosis mouse models and was significantly upregulated in fibrotic kidneys of patients with CKD." (PMID 39913299, 2025).
Sepsis (1 paper, 2020). Sepsis is defined as life-threatening organ dysfunction caused by a dysregulated host response to infection. "We found it to be associated to adult SIRS (along with ZDHHC18, as opposed to ZDHHC19 found in the sepsis pathway association analysis)." (PMID 32318053, 2020).
tumor (3 papers, 2019 to 2025). "Analysis of paired samples from TCGA revealed that ZDHHC18 was significantly overexpressed in ccRCC tumor tissues compared to adjacent normal tissues." (PMID 41357761, 2025). "ZDHHC18 was broadly expressed across multiple cell types within the tumor microenvironment, including immune and stromal populations, with moderate variability among datasets." (PMID 41357761, 2025). "In contrast, knockdown of ZDHHC18 or PTC596 injection obviously resulted in the inhibition of tumor growth and extended the survival rate of all animals that were implanted with mesenchymal GSCs." (PMID 30658672, 2019). "Additionally, ZDHHC18 was significantly upregulated in ccRCC tumor tissues, and its knockdown notably inhibited cell proliferation, migration, and invasion." (PMID 41357761, 2025). "The ZDHHC18 expression level was increased in perinecrotic and microvascular proliferative regions, and that of ZDHHC23 was associated with the leading edge and infiltrating tumor regions in GBM." (PMID 30658672, 2019). "In addition, cell–cell communication analysis using the “CellChat” package revealed complex interaction networks involving malignant epithelial cells and other cell types in the tumor microenvironment, providing further context for understanding the functional implications of ZDHHC18 in ccRCC." (PMID 41357761, 2025). "The high levels of expression of ZDHHC18 and ZDHHC23 were related to the tumor grade (IV, p < 0.01 for ZDHHC18; IV, p < 0.01 for ZDHHC23)." (PMID 30658672, 2019).
infection (1 paper, 2023). The state of being infected such as from the introduction of a foreign agent such as serum, vaccine, antigenic substance or organism. "Briefly explaining, figuratively, the initiation of infection with SARS-CoV-2 using ACE2 as a receptor for viral entry and infectivity is augmented by ZFPs like ZDHHC18, ZNF267, and ZC3H11A (seen in Omicron infection)." (PMID 38025778, 2023).
ZDHHC18 also shares sentences with these, for which no sentence is quoted: cancer (2 papers); oligodendroglioma (2); breast carcinoma (1); chronic pancreatitis (1); kidney disease (1); liver cancer (1); lung adenocarcinoma (1); lymph node metastasis (1); pancreatic cancer (1); renal carcinoma (1); schizophrenia (1); Ureteral obstruction (1).